LINC02613 (long independently transcribed non-coding RNA 2613)
Gene: Long non-coding RNA gene on chromosome 2 (38,406,335 to 38,536,853, reverse strand). Ensembl gene ENSG00000231367.
Diseases named in the same sentence as LINC02613 in open-access papers:
LINC02613 is named in the same sentence as 2 diseases in open-access papers, as found by Europe PMC text mining. Sharing a sentence is not in itself a finding about the gene and the disease. The quoted sentences say what the papers report.
breast carcinoma (1 paper, 2024). "Five ARLs (MAPT.IT1, AL133467.1, AC004585.1, AC055854.1, and LINC02613) were identified as protective factors, whereas two (LINC01614 and C6orf99) were identified as risk factors for breast cancer." (PMID 38189818, 2024).
breast tumor (1 paper, 2024). "Additionally, quantitative reverse transcription-polymerase chain reaction (qRT-PCR) analysis revealed that the expression levels of C60rf99, LINC02613, AL133467.1, MAPT-IT1, and AC004585.1 were downregulated in breast tumor tissues relative to normal breast tissues (P < 0.05)." (PMID 38189818, 2024).